SYNPR-AS1 (SYNPR antisense RNA 1)
Synonyms: LncFASA
Gene: Long non-coding RNA gene on chromosome 3 (63,421,300 to 63,645,637, reverse strand). Ensembl gene ENSG00000241359.
Diseases named in the same sentence as SYNPR-AS1 in open-access papers:
SYNPR-AS1 is named in the same sentence as 1 disease in open-access papers, as found by Europe PMC text mining. Sharing a sentence is not in itself a finding about the gene and the disease.
SYNPR-AS1 shares sentences with these, for which no sentence is quoted: cancer (1 paper).